CRP (C-reactive protein)
Diseases named in the same sentence as CRP in open-access papers (continued):
Sharing a sentence is not in itself a finding about the gene and the disease.
infection (continued). "The C-reactive protein (CRP) levels revert to preoperative levels within three weeks; however, they may be raised for a variety of reasons in addition to postoperative infection, given the high prevalence of TJA in elderly patients with concomitant diseases." (PMID 37731439, 2023). "CRP belongs to the pentraxin protein and is often used in clinical practice as a marker of infection and inflammation because its synthesis rapidly and dramatically increases after infection or tissue injury." (PMID 37834884, 2023). "However, it seems that the CRP level is essential for identifying infections and cannot currently be replaced or improved by another parameter." (PMID 37761321, 2023). "ESR and CRP are commonly used indicators to evaluate the infection degree of inflammatory diseases." (PMID 37611242, 2023). "Whether pre-emptive antibiotics are needed to abort potential infection in patients with elevation of CRP after PEG is deserved further study." (PMID 37189057, 2023). "Moreover, several patients present with episodes of unexplained fever and remarkably high C-reactive protein (CRP) values during non-invasive infections." (PMID 36319802, 2023). "Similarly, the use of biomarkers of infection during COPD exacerbation (C-reactive protein, procalcitonin) remains controversial, with research yielding inconclusive outcomes." (PMID 37828124, 2023). "We defined severe infection as an infection with C-reactive protein of 100 mg/l or higher." (PMID 37314998, 2023). "Moreover, 2/16 (12.50%) patients presented clinical signs of infection relapse, confirmed by a new CRP elevation and positive LS scan, and were discontinued from COAS and from study." (PMID 37237840, 2023). "Thus, under physiological condition, the activities of WCC and CRP are closely coordinated toward achieving an effective response to infections." (PMID 37019645, 2023). "Moreover, indicators of infection (i.e., leukocytes, erythrocyte sedimentation rate, C-reactive protein, serum amyloid A, and serum ferritin) were higher in TBIL, particularly leukocytes and serum ferritin." (PMID 37880573, 2023). "In addition to a thorough clinical assessment of the patient, the evaluation of CRP can help primary care clinicians understand if infections are self-limiting or severe, and thus evaluate the usefulness of antibiotics prescribing for LRTIs." (PMID 37324137, 2023). "In contrast, patients with acute decompensation/infection were excluded from our study and further adjustment for CRP did not alter the association between ADAMTS13-Act and hepatic decompensation." (PMID 37605068, 2023). "However, CRP appears to respond more rapidly to infection and normalize more quickly than ESR and often is the choice to track active infection and treatment." (PMID 37483708, 2023). "CRP has been mainly known as a protein that could be sensitive to a variety of changes in the host due to inflammation, infection, or trauma, including additional pathophysiological changes during tissue damage." (PMID 37627907, 2023). "The increase in the CRP value reflects the severity of the infection." (PMID 37147568, 2023). "In adjusted models, for any 10 % increase in LDH (U/L), CRP (mg/dl), and ferritin (ng/ml), there was 11.28% (95% CI: 4.19,18.85), 2.48% (95% CI: 0.49, 4.50), and 3.00% (0.59, 5.46) increase in the GM of IgG (ng/ml) at 6 months post-infection." (PMID 37293303, 2023). "However, CRP levels rise slowly and take 1-2 days to peak during infection, resulting in its low sensitivity in the early stages of the disease." (PMID 38029254, 2023). "A Chinese study evaluating 72 infection-associated AU cases reported significantly elevated white blood cells (WBC) and neutrophil counts, erythrocyte sedimentation rate (ESR), serum C-reactive protein (CRP), and procalcitonin." (PMID 37515272, 2023).
infection (continued). "CRP transcription and synthesis is primarily induced by IL-6 and results in the activation of the classical complement pathways and the recruitment of phagocytic cells to the site of infection." (PMID 37019645, 2023). "Interestingly, our findings derived from the analysis of CRP kinetic patterns, prior to infection diagnosis, also challenge the prevailing paradigm of commonly accepted patterns as prognostic indicators for ICU-acquired infections." (PMID 37834754, 2023). "As an acute-phase reactant protein, CRP indicates injury, infection, and inflammation." (PMID 38031949, 2023). "Several markers of inflammation, tissue injury and organ dysfunction, mainly of cardiac and renal tissues were altered in both groups due to the severity of infection, but more intensely in DM group, presenting higher levels of CRP, LDH, troponin, PKC, lactate and BNP." (PMID 37845766, 2023). "In addition to albumin, C-Reactive Protein (CRP) is produced in response to infection and is one of the most used markers of inflammation." (PMID 36995004, 2023). "Infection may be suspected in cases of elevated C-reactive protein (CRP) levels or elevated white blood cell count (WBC)." (PMID 36829589, 2023). "An increasing body of evidence suggests that CRP can predict various postoperative infections." (PMID 37745673, 2023). "More studies are needed to verify whether lower cut-offs for CRP better predict ongoing infection in fragile elderly." (PMID 37737163, 2023). "Thus, “three phases of subclinical infection and inflammation like incubation, early, and late convalescence phase were identified by specialized monitoring markers such as C-reactive protein (CRP) and α-1-acid glycoprotein (AGP), respectively”." (PMID 38102707, 2023). "Early after infection, IL-6 conducts the synthesis of acute phase proteins (including C-reactive protein (CRP), fibrinogen, serum amyloid protein, and haptoglobin, among others) in the liver, which orchestrate the systemic host immune response independently of the site where infection takes place." (PMID 37818368, 2023). "Furthermore, MHD patients with CRP below 40 mg/L have a sevenfold decrease in the odds of having an infection than MHD patients with CRP above 40 mg/L." (PMID 37016028, 2023). "In addition, the EBJIS criteria consider a single positive culture in an “infection likely” scenario if a second parameter (e.g., positive clinical feature or CRP) is positive." (PMID 37175046, 2023). "For instance, CRP (C-Reactive Protein), a biomarker of inflammation, could be associated to PCT to increase the medical value of the assay for infection diagnostics." (PMID 36795693, 2023). "Firm conclusions cannot be drawn, although the delayed rise of CRP as a response to infection seems to suggest that a single determination of this protein has an unacceptably low sensitivity for routine use in clinical practice, particularly when EOS is considered." (PMID 37627653, 2023). "In addition, it was demonstrated (by ROC curve analysis) that hBD2 is a superior biomarker to both PCT and CRP for the diagnosis of infection." (PMID 37296737, 2023). "Indeed, CRP levels can be raised due to auto-immune conditions, cancers, and infections, and therefore cannot with certainty identify if an inflammation is caused by a virus, bacteria, or other." (PMID 37900677, 2023). "Moreover, low CRP levels were measured in the serum of infected rats on day 180 post-infection, another finding that supports the weak inflammatory response observed." (PMID 37508953, 2023). "This study suggested that during the early phase of bacterial infection, FcαRI plays a protective role in innate immunity through its direct recognition of bacteria, and as the infection progresses, it exerts a conventional effects as a receptor in adaptive immunity mediated by binding IgA and CRP." (PMID 37564652, 2023).
infection (continued). "Given the sharp decline in cytokine levels over the critical first 7 days after delivery, we further interrogated the temporal association of MCP-1 values with clinically suspected prenatal infection and IL-6 values, as well as CRP levels, with clinically diagnosed postnatal infection." (PMID 37606448, 2023). "However, noticeably increased levels of CRP are frequently connected to pathogen- or infection-related molecular pattern recognition." (PMID 37860004, 2023). "Therefore, as described in the expert consensus, repeated acquisition of CRP levels is suggested in suspicion of early-stage infection." (PMID 37153693, 2023). "In our research, we sought to find out whether certain inflammation-related blood cell parameters could aid in improving the efficacy of early detection of infections provided by current gold-standard methods (CRP and PCT)." (PMID 37761321, 2023). "If only CRP levels are elevated, it can be inferred that the infection is in the later stages." (PMID 37510151, 2023). "CRP is a protein made by the liver that acts as an early indicator of inflammation and infection." (PMID 37763241, 2023). "In contrast, the infected control group had 60.2 ng/mL, 2.3 ng/mL, 1,073.9 ng/mL, and 532.2 ng/mL levels of IL-6, TNF-α, KC, and CRP, respectively, in the 5th h after infection, and these levels decreased by 18.5, 2.3, 10.5, and 8.4 times at the 8th h, respectively." (PMID 37293234, 2023). "In the preoperative blood test, CRP was high, indicating the presence of infection." (PMID 36627931, 2023). "The spread of infection was monitored by maternal pulse rate, fetal heart rate, TC, and CRP." (PMID 37609091, 2023). "CRP interaction with LPG thus has importance in infection of the mammalian host from the sand fly." (PMID 37720216, 2023). "If a patient is simultaneously receiving TPE daily regimen, such a fall in CRP cannot be attributed only to resolving infection but may also be due to removal during TPE." (PMID 37150798, 2023). "All patients manifested signs of infection (median CRP of 120 mg/L (IQR 81–180))." (PMID 37103058, 2023). "Hence, the anti-inflammatory properties of AG-CuNPs that significantly decreased CRP levels positively impact counteracting infection subsequences, supporting vital organ functions and general health aspects besides its antibacterial activity." (PMID 37542317, 2023). "However, in the case of a suspected infection, it is mandatory to perform blood tests and joint aspiration (white blood cell count, C-reactive protein, erythrocyte sedimentation rate, culture and microscopic examination)." (PMID 37700168, 2023). "However, as CRP was measured as part of usual care, it was a standard measurement upon admission, but thereafter only in cases of clinical indication (i.e., if an infection was suspected or to monitor progress of a present infection)." (PMID 37623168, 2023). "For the full year of 2022, IL-6 levels of suspected EOS and EOS-classified newborns (67 cases) were examined in more detail in relation to the increase in CRP levels to assess whether IL-6 can be used as a reliable early infection marker." (PMID 38255366, 2023). "Initial laboratory evaluation should include white blood cell count, C-reactive protein, and sedimentation rate as markers of infection that can be subsequently used to track treatment efficacy, and the patient, in this case, report had multiple serial CRP level checks." (PMID 38036498, 2023). "Furthermore, she had elevated C-reactive protein (CRP) (19.7 mg/dL) and procalcitonin (12.6 ng/mL) levels, suggesting worsening sacral and left lower extremity ulcers and concomitant infection." (PMID 36890459, 2023). "Phosphorylcholine is displayed by a variety of microorganisms, raising the possibility that CRP might protect against some infections." (PMID 36936978, 2023).
infection (continued). "Also, in HCV/HBV infections, it was noted that CRP levels were notably decreased, but how can an infection be in parallel with low CRP, which is supposed to be an acute phase reactant?" (PMID 37873776, 2023). "We found that adding a check by pharmacists of patients’ infection-related condition to a previously devised protocol, based on body temperature ≥ 37.5 °C or elevated CRP or WBC from baseline, before anticancer drug mixing significantly reduced anticancer drug wastage after mixing." (PMID 36650580, 2023). "CRP is a more sensitive inflammatory response protein produced by hepatocytes induced by IL-6, and its expression level increases when the body is exposed to trauma or infection." (PMID 36983320, 2023). "However, the animals with infection and aseptic reactions had significantly elevated CRP and ESR levels at all follow-up time points when compared to healthy ones." (PMID 37888163, 2023). "C-reactive protein is recognized as a marker of systemic inflammation and severe infection." (PMID 37990060, 2023). "First, some factors, including laboratory indicators (such as fast plasma glucose, fasting insulin, fasting C-peptide, and C-reactive protein), site of infection, drugs, and interventions that could be related to prognosis, were not included in this study." (PMID 37608790, 2023). "Considering the limitations of other predictors, such as CRP level elevation by infection and the effort needed to evaluate BVAS, the SS level measurement may be useful for estimating kidney biopsy findings in AAV patients in some clinical situations." (PMID 38111574, 2023). "Repeating the main analysis excluding the 28 participants who were admitted because of an infection showed a similar non-significant association between CRP and CPV (n = 76, b = 0.78, CI = −3.6, 5.5)." (PMID 37623168, 2023). "In addition, the majority of febrile pregnant women came to the hospital within 1–2 days, and CRP was elevated in the late stage (more than 24 h) of infection compared with other inflammatory markers." (PMID 37638092, 2023). "While the authors strongly suggest avoiding prescribing antibiotics when CRP values are below 20 mg/L and when the clinical assessment supports ruling out a severe infection, the degree of uncertainty, when it comes to the right cut-off values of CRP for children, is larger than in adults." (PMID 37900677, 2023). "The relatively short half-life is an advantage of both prealbumin and CRP, which could make them sensitive indicators of infection." (PMID 36670722, 2023). "The kinetics of CRP may play a useful role in critical care settings and has the potential to refine and compose predictor models to expeditiously predict these infections, ultimately reducing their impact on patient survivability." (PMID 37834754, 2023). "Other CRP lowering approaches, such as apheresis, have also shown that the therapeutic targeting of CRP does not appear to increase the risk of infection." (PMID 36468184, 2023). "If high CRP levels persist during the course of illness, further diagnostic workup should be considered to rule out serious infections." (PMID 37900677, 2023). "Therefore, IL-6 can serve as an early marker for identifying EOS and mild infections, offering a means to predict the subsequent elevation in CRP levels." (PMID 38255366, 2023). "CRP is an acute-phase protein that rises in response to inflammation or infection in the body." (PMID 37433824, 2023). "CRP typically takes 24–48 h to peak during infection development." (PMID 37239167, 2023). "Nearly half of children tested in the primary care setting can be expected to have a CRP value below 20 mg/l, in which case it is strongly suggested to avoid prescribing antibiotics when the clinical assessment supports ruling out a severe infection." (PMID 37900677, 2023). "Moreover, elevated levels of CRP in conjunction with low albumin levels indicate a decline in albumin production and increased breakdown due to inflammation or infection." (PMID 38137581, 2023).
infection (continued). "The CRP was first described by Tillett and Francis in pneumonia and with time and continuous research has been established as a reliable parameter in detecting and monitoring different types of infections." (PMID 37872533, 2023). "CRP as an acute-phase protein increases in response to inflammation, trauma, and infection." (PMID 37382699, 2023). "The WHO recommends blood ferritin concentration as a good marker of iron stores in apparently healthy individuals and in populations, with adjustment for α-1 acid glycoprotein (AGP) and/or C-reactive protein (CRP) for individuals with infection or inflammation." (PMID 36986035, 2023). "Another point to note is that CRP is an integral component of the “acute phase response” which is an early and relatively non-specific part of the innate immune response to various stressors, including trauma and infection by both bacteria and viruses." (PMID 36851633, 2023). "Increased neutrophils, ESR, CRP and total leukocyte values could be used as prognostic assays to predict the occurrence of infection." (PMID 37755950, 2023). "CRP is a nonspecific acute phase reactant protein synthesized in the liver, which is frequently used as a diagnostic parameter of infection, associated with the level of inflammation and disease severity." (PMID 37525784, 2023). "Overall, it seems that age may be a significant confounder when deciding for treatment, but even in severely affected patients with extensive infection and exceedingly high CRP levels, surgery should be initiated, if medically feasible." (PMID 37099226, 2023). "CRP, an acute phase reactant protein, is elevated in acute inflammation, tissue injury, and infection, and its levels are positively correlated with the degree of infection." (PMID 37576105, 2023). "Indeed, its levels were higher in the reactivation group and decreased together with C-reactive protein and lactate dehydrogenase after infection resolution." (PMID 36838310, 2023). "In elderly patients with femoral neck fractures, preoperative serum C-reactive protein (CRP) values might be elevated due to active infections." (PMID 37107100, 2023). "Additionally, they proved that both the WBC and CRP levels correlated with the clinical improvement of patients, i.e., with a decrease in the WBC and CRP levels, the symptoms of infection disappear." (PMID 36670722, 2023). "SAA1 and CRP are among the APP with the highest increase during infection." (PMID 37868984, 2023). "In addition, two zebrafish homologs for the human gene encoding C-reactive protein (crp2 and crp3, ENSDARG00000056498 and ENSDARG00000042613, respectively) were induced upon infection in zebrafish larvae." (PMID 36622851, 2023). "The levels of CRP are known to increase rapidly in blood plasma during infection or tissue damage." (PMID 37953798, 2023). "CRP levels are known to increase in response to injury, infection and inflammation." (PMID 38093036, 2023). "C-reactive protein is a well-known marker of systemic inflammation and severe infection." (PMID 37643201, 2023). "After observing such elevated CRP values and knowing that bacterial infections could be contributing to this event, we analyzed the frequency of secondary infections among groups during hospitalization." (PMID 35453779, 2022). "CRP is a commonly used inflammatory marker in the blood that is used to assess infection." (PMID 35350520, 2022). "There are portable rapid diagnostic testing devices for white cell count, lactate and C-Reactive protein available but assessment of their feasibility and cost effectiveness as screening for infection in routine maternity care in low resource settings is awaited." (PMID 35473664, 2022). "Particularly, peripheral inflammatory markers (PIMs) based on the differential white blood cell (WBC) count are better predictors of mortality and clinical outcomes in various medical conditions than traditional infection markers, including C-reactive protein (CRP) or total leukocyte count." (PMID 36362765, 2022).